CD44 (CD44 molecule (IN blood group))
Diseases named in the same sentence as CD44 in open-access papers (continued):
Sharing a sentence is not in itself a finding about the gene and the disease.
cancer (continued). "The expressions of CD44 and CD133 were tested to evaluate increases in cancer cell stemness after each of the PRL treatments at 12, 24, and 48 h." (PMID 41501898, 2026). "Radioresistance arises from cancer stem cell maintenance (CD133/HMGB2), TAM polarization (CSF-1R/CD44), and enhanced homologous recombination (RAD51)." (PMID 42125691, 2026). "We demonstrated that the anti-cancer efficacy of 2B7 is mediated by the inhibition of the IGF1/IGF1Rβ and OPN/CD44 signaling, both central to cancer stem cell regulation, and by suppressing immune evasion via downregulation of PD-L1 and B7-H4." (PMID 41356204, 2026). "CD44 and CD133 are common markers for identifying cancer stem cells, and high expression levels of these markers are associated with a poor prognosis and increased recurrence." (PMID 41305000, 2025). "The interaction of MIF with its receptors (CD44, CD74, CXCR4) are known drivers in late stage MM and other cancers and are involved in a variety of mechanisms, including homing to BM, pro-tumoral M0 macrophage differentiation and resistance to therapy." (PMID 41056512, 2025). "CD133 is a promising pan-cancer target, with 19 drugs currently in preclinical or phase I trials, most of which are antibody-based or CAR-T cell therapies, such as CD44/CD133-targeted CAR-T and OXS-1650." (PMID 41039172, 2025). "In conclusion, the investigation of CD44-targeted functionalized nanocarriers for NSCLC is a compelling account of advancements and breakthroughs in cancer treatment." (PMID 41367861, 2025). "Long-term P. gingivalis infection increased the expression of CD44 and CD133 antigens, well-known markers of stemness, which promoted the invasive features of infected cancer cells compared with uninfected controls." (PMID 41228271, 2025). "Three Raman tags with distinctive Raman spectra were used to report three different protein markers on individual cancer cells, with QSY21 for CD44, BHQ3 for EpCAM, and QXL680 for HER2." (PMID 39997827, 2025). "HA receptors, such as CD44, along with its downstream signaling pathways like ERK/MAPK, play a crucial role in regulating the cancer cells’ response to HA." (PMID 40178908, 2025). "HA for CD44 recognition; c(RGDyK) for integrin binding; TPP-modified MoS2–Ti3C2 for mitochondrial localization; cancer cell membrane cloaks; bacterial colonization of hypoxia enabling cavitation." (PMID 41470489, 2025). "In numerous in vivo and in vitro studies, a variety of cancer-related mRNAs have been identified, including PTEN, ACTB, MAPK4, MKI67, c-MYC, and CD44." (PMID 40082414, 2025). "Cell communication analysis indicated strong interactions between CD2AP+ cancer cells and monocytes, predominantly mediated by the APP-CD74, MIF-CD74_CD44, and SCGB3A2-MARCO pathways." (PMID 41425578, 2025). "The upregulated ABCB1, ZEB1, and CD44 were engaged in microRNA regulation in cancer, SOX2 and KLF4 were engaged in pluripotency of stem cells, and TWIST1 and CD44 contributed to proteoglycans in cancer." (PMID 40251609, 2025). "NIR-PIT can target any of the antigens expressed on the surface of the cancer cell, including CD44 and CD133 as positive markers of cancer stem cells." (PMID 40574027, 2025). "Our study included EOT with different biological behaviors, and therefore we selected CD44 and CD133 as the most widely used and confirmed to be specific to distinguish CSC from other cancer cells in various tumors." (PMID 40332380, 2025). "We demonstrate expression of the markers CD24, CD44, CD133 and ALDHA1A, which are well known to characterize cancer stem cells." (PMID 41310103, 2025). "Other authors have also identified a correlation between high levels of CD44 expression and various adverse outcomes in patients with HNSCC, including cancer recurrence, poor response to radiotherapy, regional metastasis, and reduced overall survival." (PMID 40738059, 2025).
cancer (continued). "Targeting the CD44/SPP1 and integrin/SPP1 axes represents a promising strategy for cancer therapy, as these interactions play critical roles in the TME." (PMID 41391064, 2025). "Another approach involves targeting HA receptors, such as CD44 and RHAMM, with monoclonal antibodies and small-molecule inhibitors to suppress cancer cell migration and invasion." (PMID 40507943, 2025). "Cancer cells that undergo epithelial to mesenchymal transition (EMT) acquire stem cell-like characteristics and exhibit increased CD44 expression accompanied by enhanced invasiveness." (PMID 40221767, 2025). "We examined the apoptotic effects of thymoquinone, its role in inducing autophagy, its ability to modulate ROS, and the expression of CD44+, CD133+, and CD147+ cancer stem cells in both models." (PMID 41305000, 2025). "For comparison, we also tested mouse CD44-targeted NIR-PIT (CD44-NIR-PIT), which is known to affect non-cancer cells." (PMID 40792441, 2025). "Concordantly, the expression of cancer stemness-related genes, such as LGR5 and CD44, was significantly reduced at the mRNA and protein levels in TetOff cells upon expressing wt-Cdx1/2." (PMID 40399276, 2025). "A deeper understanding of the role of CD44 in CSC biology and ferroptosis resistance is essential to develop innovative strategies to combat treatment-resistant cancers." (PMID 40259468, 2025). "CD44 has been shown to physically bind to the vimentin N-terminal head domain in HUVEC cells, and both proteins are overexpressed in cancer cells." (PMID 40806710, 2025). "Previous studies have shown that anti-cancer immune responses were highly induced by NIR-PIT targeting EGFR, CD29, and CD44." (PMID 39751657, 2025). "After Nab-PTX + pembrolizumab, MDSCs cocultured with TTN-KO cancer cells attenuated apoptosis and increased CD24 + CD44 + cell subpopulations in TNBC." (PMID 41326912, 2025). "Their work allowed cancer cell isolation/enrichment, optical imaging, multiplex SERS detection for four cancer biomarkers (EpCAM, HER2, CD44, and IGF1R), as well as molecular profiling of various breast cancer cell lines." (PMID 39997827, 2025). "For instance, lncRNA CTC-490G23.2 is implicated in the regulation of mRNA alternative splicing of CD44, a mesenchymal CSC marker in multiple cancer types." (PMID 39937018, 2025). "A subpopulation of CSC was isolated from HCT116 treated with TNF-β (mainly CD44+ and ALDH+ cancer stem cells)." (PMID 39859345, 2025). "Interestingly, we identified a cancer cell-specific ASE in the cell adhesion gene CD44, which represents a glycoprotein involved in cell adhesion and migration that provides a textbook example of how AS can generate various isoforms with properties that may have distinct biological effects." (PMID 41273175, 2025). "Previous studies demonstrated that CD44 interacts with EGFR potentiating MAPK/ERK pathway 13, 29 and TGFβR1 30 in human cancer cells." (PMID 40860188, 2025). "Next, the expression profiles of CD44, FGF2, FGF10, KDM6A, FN1, and MMP2 were evaluated using the OcoDB database across different clinical stages, age groups, and racial categories in cancer patients." (PMID 39833941, 2025). "The contrasting roles of CD44 and MMP2 in proliferation and migration emphasize the complexity of gene functions in cancer." (PMID 39833941, 2025). "Functional studies suggested that B7-H3 potentiates EMT and cancer stemness by reducing E-cadherin and inducing N-cadherin vimentin, CD133, CD44 and OCT-4." (PMID 41233805, 2025). "Curcumin reduces the proportion of CD44+/CD24+ cells, which are considered cancer stem-like cells, in BC cell lines." (PMID 40443562, 2025). "Key molecules for cancer progression were inhibited (IL6, IL4, CXCL8, CXCR4, CXCL12; ICAM1, CD44 and BCL2), and pro-apoptotic BAD was activated." (PMID 41595551, 2025). "Ciclesonide reduced TNBC cell growth and promoted apoptosis, resulting in fewer CD44+/CD24− and ALDH+ cancer cells." (PMID 40687439, 2025).
cancer (continued). "miR34a targets multiple oncogenic genes, such as Cluster of Differentiation 44 (CD44) and Mesenchymal–Epithelial Transition factor (c-MET), by suppressing cell proliferation, metastasis, and cancer growth." (PMID 41150792, 2025). "In some cases, CAF markers, such as CD44, or CAF isoforms, like CD10 + GPR77 + CAFs, help to maintain the stemness of cancer cells, thus promoting chemoresistance." (PMID 40369674, 2025). "In oral, pancreatic, breast, and colon cancers, miR-21 enhances cancer stem cell survival, proliferation, and invasion by targeting stemness markers, including OCT4, SOX2, CD133, and CD44, as well as signaling pathways such as Wnt and AKT/ERK1/2." (PMID 40710326, 2025). "EpCAM, HER2, CD44, and IGF1R were simultaneously detected and distinguished on four three different cancer cells lines (SK-BR-3, MDA-MB-231, and MCF-7)." (PMID 39997827, 2025). "Cancer-related ligand receptors, such as CD166, CD318, and CD44, are currently being explored for the treatment of many solid tumors." (PMID 39996744, 2025). "The relationship between drug-tolerant residual cancer cells and cancer stem cell (CSC) properties has attracted attention, with the presence of CSC markers such as LGR5- and CD44-positive cells being reported in colorectal cancer." (PMID 40537472, 2025). "Current CSC markers, including CD44, CD24, and ALDH, exhibit variable expression patterns across different cancer types and lack specificity, complicating the prediction of treatment responses." (PMID 40821110, 2025). "Before CD44 was discovered to be a PRG4 receptor, its relevance in carcinogenesis was extensively acknowledged, being related to cancer stemness, increased traits of aggressiveness, and resistance to drugs in a spectrum of solid tumors including HCC." (PMID 41327374, 2025). "In the present study, we evaluated the expression of the immune checkpoints CD276, CD44, TNFRSF14, and VSIR across a range of cancer tissues." (PMID 40727469, 2025). "Additionally, CD44+ cancer stem cell abundance was associated with worse RFS, but not MFS." (PMID 40940877, 2025). "Using flow cytometry, we examined the proportions of CD44+ and CD133+ in cancer cells (quadrant gating on live cells, gate thresholds set accounting for single stainings)." (PMID 40160820, 2025). "CD44, individually or together with other molecules (CD24, CD133, CD34, and c-Met), can be a key marker for cancer stem cells." (PMID 39851489, 2025). "The cancer cell stemness reprogramming factors OCT4, KLF4 and c‐MYC and the stem cell marker CD44 were significantly increased in Huh7 cells on the 14th day after HBx overexpression." (PMID 40717222, 2025). "The membrane proteins such as CD44 and CD47 were examined by Western blotting since they play a crucial role in cancer metastasis." (PMID 40274835, 2025). "CD44-targeted PLGA-DTX NPs represent a dual-targeting therapeutic strategy, overcoming both cancer stem cell-driven chemoresistance and TAM-induced immunosuppression." (PMID 41280929, 2025). "The expression of both CD44 and CD109, which act as putative cancer stem cell biomarkers, facilitate cancer progression and resistance to treatment, making them promising targets for therapeutic strategies in various cancers." (PMID 40227788, 2025). "The SPP1-CD44 interaction was identified as the most influential in cancer progression, with SPP1 highly expressed in TAMs and CD44 overexpressed in neoplastic-stemness cells." (PMID 40076844, 2025). "A notable decrease in cell growth, the CD44+CD24‐ population, and the EMT status was observed in the recipient cancer cells." (PMID 40059964, 2025). "Our experimental results indicate that NOD2 influences cancer stemness properties in GBM cells, as evidenced by the reduced expression of CSC markers CD44 and CD133 following the NOD2 knockdown." (PMID 40868292, 2025).
cancer (continued). "The examination of CD44 as a biomarker revealed its diverse involvement in NSCLC, including its molecular attributes, its correlation with cancer stem cells, and its prognostic significance." (PMID 41367861, 2025). "CD44, together with three other biomarkers (GC, CRP, and ITIH3), showed the best performance in discriminating regional cancer (lymph node invasion) from localised cancer." (PMID 41440277, 2025). "Our results showed that MBZ significantly down-regulated cancer stemness markers, including CD24, CD44, and EpCAM, in both OVCAR3 and OAW42 cells, but the effects were more pronounced in OVCAR3 cells." (PMID 39851541, 2025). "Protein expression of the cancer stem markers CD44 and CD133, as well as OCT4, was also assessed in various cancers, including HCC and OPCs." (PMID 41011230, 2025). "CD44 and CD24 are cell surface proteins, and their expression patterns are used to identify and characterize cancer stem cells (CSCs)." (PMID 40227834, 2025). "Our data showed that the co-expression of CD44 and CD133, as the most frequently analyzed putative cancer stem cell markers, ranged from 0.2% to 55.2% (median 1.7%)." (PMID 41303421, 2025). "Among all of these, MMP2, MMP9, FN1, CD44, SERPINE1, and CAV1 are the most famous collaborators with PLAUR in the cell migration of multiple cancer types." (PMID 38396677, 2024). "The primary binding partner for CD44 is hyaluronic acid (HA), a plentiful component of the ECM found in stromal and cancer cells." (PMID 39338413, 2024). "For example, responsible genes in the regulation of cancer cell survival and proliferation such as STAT1, STAT5A, CD44 and BCL2 are upregulated." (PMID 39056676, 2024). "We believe that GBP1 and HNRNPK bind to regulate the expression of CD44 protein through A3SS alternative splicing form, and finally play a role in promoting cancer." (PMID 38167153, 2024). "Conditioned medium from chemotherapy-treated MAFs raised the expression of cancer stem cell markers, including ABCG2 and CD44, in the recipient mPDOs." (PMID 38791392, 2024). "The interaction between SPP1 and CD44 has been widely reported in cancer for immune cell infiltration, and those studies also highlighted the ability of SPP1-CD44 interaction to modulate cell adhesion and movement." (PMID 39372920, 2024). "CSCs exist as a small population of cancer cells characterized by the expression of such surface markers as CD24, CD44, and/or CD133." (PMID 38812048, 2024). "Therefore, inhibiting CD44 could be a potential therapeutic target for cancer treatment." (PMID 38672650, 2024). "We investigated the effect of polystyrene nanoparticles (PSNPs) on cancer cell stemness using flow cytometric analysis of CD24, CD44, ABCG2, ALDH1 and their combinations." (PMID 38787133, 2024). "Certain HAIMs, including CD44, TSG-6, LYVE-1, RHAMM, HAPLN3, NCAN, and VCAN, can facilitate the proliferation of cancer cells." (PMID 38791985, 2024). "Our findings support the notion that CD44 isoform 4 is an anti‐metastasis therapeutic target and give valuable insight into isoform specificity in CRC that is essential for unique cancer cell states and, thus, cancer phenotypes." (PMID 37849446, 2024). "Quantitative real-time PCR analysis confirmed that the expression levels of cancer stem cell markers, including CD133 and CD44, in the spheres were significantly elevated compared to those in adherent cells." (PMID 39702326, 2024). "Organoid formation and expression of cancer stem cell markers such as ABCG2, NANOG, and CD44 were altered by conditioned media from treated MAFs." (PMID 38791392, 2024). "Conventional methods use antibodies such as CD44 and CD63 to isolate cancer cells or cancer-related substances, such as exosomes, from biological fluids (e.g., blood) for subsequent analysis." (PMID 38400238, 2024).
cancer (continued). "RT-qPCR revealed that the expressions of several markers, includingCD24,CD44,CD133,CD155,CD166,OCT4, andABCG2, which are indicators of cancer stemness, were decreased in HCT116-shPCAT6 and SW480-shPCAT6 cells." (PMID 38606479, 2024). "The objective of this study is to evaluate solCD44 and TP levels in 150 participants with high cancer risk during annual visits over 4 years and to follow prospectively to determine if CD44 and TP are effective early biomarkers for OOPSCC and other cancers." (PMID 39030509, 2024). "Detection of differential markers subtyped the cells of mesenchymal origin (vimentin, desmin, cadherin-11, podoplanin, CD74, S100A4, CD44, FAP), which vary according to the functional differentiation and specialization in sites of cancer tissue." (PMID 39575252, 2024). "Our study is the first to date to explore associations of several reproductive variables with the expression of breast stem cell markers CD44, CD24, and ALDH1A1 in cancer-free women." (PMID 38577336, 2024). "IL-18 has been shown to upregulate CD44, VEGF, and MMP-9 in an NF-κB-dependent manner, which increases cancer’s metastatic properties." (PMID 39451257, 2024). "CSC markers like CD44, CD133, and L1CAM are considered to be poor prognostic indicators in various cancers." (PMID 39148690, 2024). "Signaling from CAFs increased protein levels of CSC markers CD44, Nanog, ALDH1/2, and SOX9, and promoted clonogenicity and EMT phenotypes of cancer cells." (PMID 38737455, 2024). "The molecular mechanismsof cancer pathway genes were deactivated,including COX, GJA1, CD44, FGF9, and CCND1." (PMID 38481680, 2024). "The immunohistochemical analysis revealed significantly higher expression of CD44, MYC, IL17A, CXCL1, FCGR3A, SPP1, and IL1A in cancer tissues, while CXCL12 and CCL5 showed significantly higher expression in adjacent normal tissues." (PMID 39767563, 2024). "When VCAN forms complexes with molecules such as HA and CD44, the viscosity and elasticity of the ECM increase, shaping an environment conducive to cancer cell proliferation and migration." (PMID 38791985, 2024). "In addition, we revealed the expression and distribution heterogeneity of the CD44 gene in different cancers at the single-cell level, conducted pseudotime trajectory analysis on CD44 gene expression, and characterized the communication of CD44+ monocytes and CD44- monocytes with other cells." (PMID 38590654, 2024). "In the past decades, several studies have shown that CD44 and STAT3 cooperate with each other in cancer promotion." (PMID 38385088, 2024). "Cancer stem cells are identified using cell surface markers and although no markers are exclusively specific to LCSCs15, we identified CD24, CD44, CD133, and EpCAM that are correlated to CAR expression." (PMID 39730609, 2024). "Through the increase in CD44 and ALDH1 protein expression, GRHL2 stimulates the enrichment of cancer stem cells in the population." (PMID 39199676, 2024). "For example, CD44, a cell surface marker for cancer stem cells, interacts with PKM2 and thereby enhances the glycolytic phenotype of cancer cells." (PMID 39408832, 2024). "CoQ0 prevents cancer stem-like characteristics (upregulated CD24 expression and downregulated CD44, ALDH1, and OCT4) under normoxia and/or hypoxia." (PMID 38904007, 2024). "CD44, RHAMM, PHBPs, and HAPLNs are widely expressed in various tissues and cell types, including certain cancer cells." (PMID 38791985, 2024). "They found overexpression of several markers and receptors, including CD44, CD73, CD90, CD105, and CD166, present in both benign and malignant tumors." (PMID 39684268, 2024). "High expression of CD44/CD24 cells are recognized as a subpopulation with higher clonogenic and tumor initiation potential leading to aggressive cancer types and poor prognosis." (PMID 38787133, 2024). "CD44 — a cell surface adhesion molecule — is overexpressed in cancer stem cells (CSC) and used as a CSC marker of BC and other cancer types." (PMID 37692502, 2024).